FOCAD (focadhesin)
Description:
Required for the maintenance of SKIC2 and SKIC3 proteostatic levels in the liver. May be involved in the regulation of RNA degradation by the exosome complex. Potential tumor suppressor in gliomas.
Synonyms: KIAA1797; FLJ20375; SCOLIV
Tractability: PROTAC: ubiquitination databases record sites on it; its protein half-life has been measured.
Gene: Protein-coding gene on chromosome 9 (20,658,305 to 20,996,161, forward strand). Ensembl gene ENSG00000188352.
Subcellular location: Cell junction, focal adhesion; Cytoplasm, cytosol
Subcellular location (Human Protein Atlas): Cytosol
Gene Ontology:
Molecular function: protein binding
Biological process: regulation of post-transcriptional gene silencing
Cellular component: cytosol; focal adhesion
Genetic constraint (gnomAD): Loss-of-function variants: 132 observed, 159.27 expected, observed/expected ratio (o/e) 0.83, 90% interval 0.72 to 0.96. The upper end of that interval is the gene's LOEUF score, 0.96, which puts it in group 4 of 6, group 1 being the genes least tolerant of losing a copy. Missense variants: 2,171 observed, 1,783.6 expected, observed/expected ratio (o/e) 1.22, 90% interval 1.17 to 1.26. Synonymous variants: 727 observed, 654.32 expected, observed/expected ratio (o/e) 1.11, 90% interval 1.04 to 1.18.
Homologues: Orthologues: chimpanzee FOCAD (99% identical), macaque FOCAD (97% identical), pig FOCAD (91% identical), rabbit FOCAD (90% identical), dog FOCAD (87% identical), guinea pig FOCAD (87% identical), rat Focad (84% identical), mouse Focad (84% identical), tropical clawed frog focad (59% identical), zebrafish focad (50% identical), Drosophila melanogaster CG3520 (16% identical).
Diseases named in the same sentence as FOCAD in open-access papers:
FOCAD is named in the same sentence as 27 diseases in open-access papers, as found by Europe PMC text mining. Sharing a sentence is not in itself a finding about the gene and the disease. The quoted sentences say what the papers report.
glioma (6 papers, 2014 to 2024). A benign or malignant brain and spinal cord tumor that arises from glial cells (astrocytes, oligodendrocytes, ependymal cells). "FOCAD protein was first described to be encoded by KIAA1797 gene as a novel component of the focal adhesion complex to co-localize and interact with vinculin in glioma cells." (PMID 34685504, 2021). "In a previous study, FOCAD had been identified as a tumor suppressor gene in glioma, the loss of which might promote aggressiveness, enhance microtubule assembly and accelerate the G2/M phase." (PMID 36184622, 2022). "FOCAD is a poorly characterized protein whose loss is associated with glioma and colorectal cancer." (PMID 32048998, 2020). "FOCAD was also found to possess tumor suppressor function to inhibit colony formation, migration, invasion and tumorigenicity in glioma cells." (PMID 34685504, 2021). "Among the other genes comprised in the deleted region, FOCAD has been shown deleted in glioma tumors." (PMID 24884915, 2014). "Interestingly, MIR-491’s host gene, KIAA1797/FOCAD, was well recognized to function as tumor suppressor gene of glioma." (PMID 27905892, 2016). "The host gene of miR-491-5p, FOCAD (KIAA1797) gene, was recognized as a tumor suppressor gene in glioma cells." (PMID 34685504, 2021). "Interestingly, both miR-491-5p and FOCAD has been reported to regulate FOCAD adhesion signaling in OSCC and glioma cells, respectively." (PMID 34685504, 2021).
astrocytoma (2 papers, 2019 to 2025). "The human DUF3037 protein KIAA1797 was named Focadhesin, because its GFP fusion protein has been detected in focal adhesion points of astrocytoma cells." (PMID 31455787, 2019).
Cirrhosis (2 papers, 2025). A chronic disorder of the liver in which liver tissue becomes scarred and is partially replaced by regenerative nodules and fibrotic tissue resulting in loss of liver function. "FOCAD variants have been reported in cases of pediatric cirrhosis and liver failure, and although there are limited data regarding this genetic variant, an international case series described 14 cases with variable hepatic and extrahepatic abnormalities." (PMID 40662096, 2025). "Biallelic mutations in the FOCAD gene have been recognized as causative agents of severe congenital liver disease, resulting in cirrhosis and extrahepatic manifestations." (PMID 40870862, 2025).
Alzheimer disease (1 paper, 2021). A progressive, neurodegenerative disease characterized by loss of function and death of nerve cells in several areas of the brain leading to loss of cognitive function such as memory and language. "FOCAD is a focal adhesion protein that has tumor suppressor properties and genetic variants of FOCAD are associated with Alzheimer’s disease." (PMID 34445083, 2021).
colon adenocarcinoma (1 paper, 2022). "The results showed that FOCAD was a frequently mutant gene (6%) in colon adenocarcinoma." (PMID 36184622, 2022).
cryptogenic cirrhosis (1 paper, 2025). "One patient with hepatic steatosis had homozygous VUS in the TMEM199 gene, and another with cryptogenic cirrhosis had homozygous VUS in the FOCAD gene." (PMID 40870862, 2025).
leukemia (1 paper, 2023). A malignant (clonal) hematologic disorder, involving hematopoietic stem cells and characterized by the presence of primitive or atypical myeloid or lymphoid cells in the bone marrow and the blood. "We identified recurrently affected genes by SVs, such as FOCAD/HACD4, MANBA, and SFMBT2 that were validated by long-read sequencing and/or RNA-seq in at least 1 leukemia." (PMID 37469802, 2023).
non-small cell lung carcinoma (1 paper, 2021). A group of at least three distinct histological types of lung cancer, including non-small cell squamous cell carcinoma, adenocarcinoma, and large cell carcinoma. "The sensitivity of non-small cell lung cancer (NSCLC) cells to cysteine deprivation-induced ferroptosis could be regulated by nuclear factor-erythroid 2-like 2 (NRF2) via the FOCAD-FAK signaling pathway." (PMID 35096011, 2021).
cancer (8 papers, 2017 to 2025). A tumor composed of atypical neoplastic, often pleomorphic cells that invade other tissues. "Together, our findings indicate PELO as a promising therapeutic target for a large patient population with cancers characterized as MSI-H with deleterious TTC37 mutations or with biallelic 9p21.3 deletions involving FOCAD." (PMID 39910293, 2025). "Loss of FOCAD could enhance microtubule assembly and accelerate G2/M phase progression to promote cancer aggressiveness and to worsen clinical outcomes in astrocytic gliomas." (PMID 34685504, 2021). "We are the first to demonstrate that both miR-491-5p and FOCAD function as tumor suppressors to inhibit cancer stemness, epithelial-mesenchymal transition, drug resistance, cell migration/invasion, and pulmonary metastasis etc. in TNBC." (PMID 34685504, 2021). "We found that miR-491-5p could be an intronic miRNA processed from FOCAD gene and first indicated that FOCAD/miR-491-5p inhibit cancer stemness, EMT, drug resistance, cell migration and invasion as well as pulmonary metastasis etc. in TNBC." (PMID 34685504, 2021). "Targeting the novel FOCAD/miR-491-5p/RABIF/MMP signaling pathway could be a promising strategy to overcome cancer stemness and drug resistance in TNBC to improve treatment efficacy." (PMID 34685504, 2021). "In addition, FOCAD played a tumor suppressor role in regulating cancer stemness, migration/invasion, and lung metastasis in TNBC." (PMID 34685504, 2021). "In 9p21.3-deleted cancers, PELO dependency emerges from biallelic deletion of the 9p21.3 gene FOCAD, a stabilizer of the superkiller complex (SKIc)." (PMID 39910293, 2025). "We found that the cancer patient treatment-relevant relation between PELO and FOCAD, or the experimentally identified interactions between SLC7A2 and SLC7A1, or SLC7A6 and SLC7A1 were best predicted upon combinatorial normalization (Dataset EV1)." (PMID 40263591, 2025). "Copy number deletions of cancer suppressor genes (including CDKN2A/B, FOCAD, NF2, etc.)are always accompanied by adjacent functional genes (including MTAP, MLLT3, etc.)deletion that synergistically contributes to oncogenesis." (PMID 37033966, 2023). "Further, we demonstrated that miR-491-5p could be an intronic miRNA processed from the FOCAD (KIAA1797) gene and identified that the focadhesin (FOCAD) protein played a tumor suppressor role in repressing cancer stemness, cell migration, tissue invasion, and pulmonary metastasis in TNBC." (PMID 34685504, 2021).
tumor (8 papers, 2016 to 2024). "Previous studies have shown that FOCAD is potentially a tumor suppressor in CRC, lung cancer, and astrocytoma." (PMID 36184622, 2022). "Then, integrated with the proteomic datasets from the Clinical Proteomic Tumor Analysis Consortium (CPTAC) (n = 98), we revealed that the increased ubiquitination of FOCAD at Lys583 and Lys587 was potentially associated with patient survival." (PMID 36184622, 2022). "Consistently, our discoveries in this study also revealed that FOCAD was one probable tumor suppressor in CRC." (PMID 36184622, 2022). "On the basis of these findings, we further explore the possible tumor suppressor role of FOCAD/miR-491-5p in TNBC." (PMID 34685504, 2021). "In the present study, we unveiled the novel tumor suppressor role of FOCAD/miR-491-5p via targeting RABIF/MMP signaling in TNBC for the first time." (PMID 34685504, 2021). "In conclusion, our study shed light on the novel tumor suppressor role of FOCAD/miR-491-5p to target RABIF/MMP signaling in TNBC." (PMID 34685504, 2021). "Another candidate at 9p21.3 is FOCAD, located ~350Kb downstream of the peak SNP, which is a potential tumor suppressor highly expressed in brain tissues." (PMID 34411106, 2021). "TNFAIP8 and FOCAD candidate genes are known to play a role in immune homeostasis and tumor suppression." (PMID 31379916, 2019). "In this study, we reported the novel tumor suppressor function of FOCAD/miR-491-5p in TNBC." (PMID 34685504, 2021). "This study identifies a novel tumor suppressor role for FOCAD/miR-491-5p in TNBC." (PMID 34685504, 2021).
FOCAD also shares sentences with these, for which no sentence is quoted: breast carcinoma (3 papers); colorectal cancer (3); anaplastic astrocytoma (1); dysplastic nevi (1); extraskeletal osteosarcoma (1); glioblastoma (1); Hepatic steatosis (1); Hypertension (1); liver cirrhosis (1); liver disease (1); liver failure (1); lung carcinoma (1); lymphoepithelial carcinoma (1); male infertility (1); melanoma (1); ovarian carcinoma (1); prostate carcinoma (1).